OR4C3 (olfactory receptor family 4 subfamily C member 3)
Description:
Odorant receptor.
Synonyms: OR11-98
Tractability: Antibody: UniProt places it where antibodies can reach, with medium confidence; UniProt predicts a signal peptide or a membrane-spanning region; its Gene Ontology location is reachable by antibodies, with medium confidence. PROTAC: ubiquitination databases record sites on it.
Gene: Protein-coding gene on chromosome 11 (48,324,920 to 48,325,955, forward strand). Ensembl gene ENSG00000176547.
Subcellular location: Cell membrane
Pathways (Reactome):
Sensory Perception: Expression and translocation of olfactory receptors
Gene Ontology:
Molecular function: olfactory receptor activity; G protein-coupled receptor activity
Biological process: detection of chemical stimulus involved in sensory perception of smell; G protein-coupled receptor signaling pathway
Cellular component: plasma membrane; membrane
Genetic constraint (gnomAD): Loss-of-function variants: 1 observed, 0.85 expected, observed/expected ratio (o/e) 1.17, 90% interval 0.28 to 1.9. That is too few expected variants to judge how well the gene tolerates losing a copy. Missense variants: 439 observed, 364.17 expected, observed/expected ratio (o/e) 1.21, 90% interval 1.11 to 1.3. Synonymous variants: 186 observed, 142.37 expected, observed/expected ratio (o/e) 1.31, 90% interval 1.16 to 1.48.
Homologues: Orthologues: rabbit OR4C3 (87% identical), dog OR4C26 (85% identical), mouse Or4c3 (85% identical), rat Or4c3 (84% identical). Paralogues in human: OR4C15 (64% identical), OR4C13 (62% identical), OR4C12 (61% identical), OR4C46 (61% identical), OR4A15 (60% identical), OR4C5 (60% identical), OR4A5 (60% identical), OR4A47 (59% identical), OR4C6 (59% identical), OR4X2 (58% identical), OR4A8 (57% identical), OR4A16 (57% identical), and 116 more.
Diseases named in the same sentence as OR4C3 in open-access papers:
OR4C3 is named in the same sentence as 3 diseases in open-access papers, as found by Europe PMC text mining. Sharing a sentence is not in itself a finding about the gene and the disease.
OR4C3 shares sentences with these, for which no sentence is quoted: ciliary dyskinesia (1 paper); glioblastoma (1); tumor (1).